SPHK1 (sphingosine kinase 1)
Diseases named in the same sentence as SPHK1 in open-access papers (continued):
Sharing a sentence is not in itself a finding about the gene and the disease.
endothelial dysfunction (4 papers, 2017 to 2025). In vascular diseases, endothelial dysfunction is a systemic pathological state of the endothelium (the inner lining of blood vessels) and can be broadly defined as an imbalance between vasodilating and vasoconstricting substances produced by (or acting on) the endothelium. "Despite aggravated endothelial dysfunction, the pro-calcific mediator angiotensin II has a reduced hypertensive effect in Sphk1-deficient mice." (PMID 39899071, 2025).
endotoxemia (4 papers, 2012 to 2021). "While there was a 4-fold increase in CD14 expression, Sphk-1 only increased by 2-fold indicating that additional signaling components are likely to be involved in the hyperinflammatory state associated with endotoxemia in the aged." (PMID 23817990, 2013). "In the current study, we focused on the potential role of Sphk-1 in the hyperinflammatory response observed in aged animals subjected to endotoxemia." (PMID 23817990, 2013). "In summary, in the present study, increased expression of Sphk-1 was identified in young and aged animals subjected to endotoxemia compared with their respective Sham groups." (PMID 23817990, 2013). "To determine the mechanism by which the inflammatory response is exacerbated in aged rats in comparison with young rats, we examined gene expression of Sphk-1 in hepatic tissues of the young and aged animals during endotoxemia." (PMID 23817990, 2013). "Results of the present study indicated that increased Sphk-1 expression in the liver in response to endotoxemia mediates the hyperinflammatory state observed in aged animals." (PMID 23817990, 2013). "Increased C5L2 expression on inflammatory cell surface induced by Sphk1, in contrast, appears to be beneficial in mouse endotoxemia." (PMID 22355325, 2012). "Genetic deletion of Sphk1, but not Sphk2, in mouse caused aggravation of LPS-induced lung injury, suggesting a protective role for SPHK1/S1P signaling against endotoxemia." (PMID 31842752, 2019). "Therefore, it is indicated that Sphk-1 contributes to age-related hyperinflammation in endotoxemia." (PMID 23817990, 2013). "Results of the present study are consistent with this proposed signaling pathway, whereby concomitant increases in Sphk-1, CD14 and TNF-α were identified in hepatic tissues of animals subjected to endotoxemia." (PMID 23817990, 2013). "For the Sphk1 function uncovered here, the maintenance of S1P plasma levels in endotoxemia, no adaptive compensation appears to have occurred." (PMID 22355325, 2012). "However, results of the current study collectively indicate that the hyperinflammatory state previously observed during endotoxemia in the aged may, in part, be due to the increase in Kupffer cell CD14 expression, leading to increased Sphk-1 and subsequent increases in TNF-α." (PMID 23817990, 2013).
esophageal squamous cell carcinoma (4 papers, 2013 to 2024). Esophageal squamous cell carcinoma (ESCC) is a type of esophageal carcinoma (EC) that can affect any part of the esophagus, but is usually located in the upper or middle third. "Another study demonstrated that as a ceRNA, LINC00514 indirectly upregulates the expression of SPHK1 to promote the progression of esophageal squamous cell carcinoma by absorbing miR-378a-5p42." (PMID 38172247, 2024).
liver disease (4 papers, 2017 to 2022). "SphK1 expression was 12-fold higher in human subjects with chronic liver disease than in normal controls (12.55 ± 6.1-fold vs control; P < .01), and this observation held true for different etiologies of liver disease." (PMID 28363640, 2017).
mesothelioma (4 papers, 2012 to 2022). A usually malignant and aggressive neoplasm of the mesothelium which is often associated with exposure to asbestos. "Overexpression of SphK1 is linked to many cancer types, including prostate, colorectal, brain, breast, liver, mesothelioma, and other lung diseases and has been identified as oncogenic due to “gain of function” in preference to any identifiable mutations." (PMID 36532885, 2022). "The endogenous role of SphKs on control (Met5A) and mesothelioma (H2691 and H2461) cell proliferation was investigated using a commercially available inhibitor of SphK1 and SphK2, namely SphK-I2." (PMID 23028939, 2012). "In contrast to the protein expression, mRNA levels of both SphK1 and SphK2 were higher in mesothelioma cell lines compared to control Met5A." (PMID 23028939, 2012). "Analyses of whole cell lysates by Western blots revealed that SphK1 protein expression was elevated in the mesothelioma cell lines (∼2 to 4 fold) compared to Met5A." (PMID 23028939, 2012). "We also tested the effects of SphK1 and SphK2 downregulation on generation of S1P in control Met5A and mesothelioma H2691cells." (PMID 23028939, 2012). "In the current study, we define the functional consequence of the down-regulation of SphK1 on the growth of mesothelioma cells and investigated the potential link between SphK1 and acetylation of H3 and H4 histones on mesothelioma cell proliferation." (PMID 23028939, 2012). "The expression of SphK1 was significantly higher (>4 fold) in mesothelioma tumors of epithelioid and sarcomatoid origin in contrast to weaker expression in normal tissue samples." (PMID 23028939, 2012). "Having established a role for SphK1 in mesothelioma cell proliferation, we then investigated if serum stimulated S1P generation in mesothelioma cells." (PMID 23028939, 2012). "Although, earlier studies have shown that SphK1 is involved in tumor growth and cancer cell proliferation, we provide evidence for the first time that SphK1-mediated histone acetylation as a necessary step in regulating mesothelioma cell proliferation." (PMID 23028939, 2012). "Since SphK1 is known to be involved in tumorigenesis, the expression of both SphK1 in normal (n = 13), and mesothelioma tumor tissues (46 epithelioid and 13 sarcomatoid) was determined." (PMID 23028939, 2012). "Here, we propose that SphK1 in is an ideal target candidate in the development of mesothelioma therapeutics." (PMID 23028939, 2012). "We also knocked down protein expression of SphK1 and SphK2 with SphK1 and SphK2 specific siRNA in Met5A and H2691 mesothelioma cell lines." (PMID 23028939, 2012). "Another important finding made in the present study is the role played by SphK1 in the acetylation of H3 and H4 histones in mesothelioma cells." (PMID 23028939, 2012). "It is possible that SphK1 in conjunction with S1P many have a similar role to that of SphK2 in modulating HDACs in mesothelioma, which is currently under investigation." (PMID 23028939, 2012). "Relative levels SphK1 and SphK2 transcripts normalized to 18S were significantly higher in mesothelioma cells lines (H2691, H2461, H513) compared to Met5A." (PMID 23028939, 2012). "SphK1 has been identified as a novel target for mesothelioma, and here we show that benign and mesothelioma epithelioid cell lines express detectable levels of SphK1b, whereas only SphK1a is detectable in biphasic mesothelioma cell lines." (PMID 36532885, 2022). "In a mouse model of this disease, the granulomatous inflammation (which was considered as a nearly mesothelioma like symptom) was greatly attenuated in SphK1−/− mice as compared to SphK1+/+ mice indicating the possibility of targeting SphK1 for the treatment of mesothelioma." (PMID 28352271, 2017).
mesothelioma (continued). "While investigating the potential mechanisms underlying mesothelioma cell proliferation, we noted a significant increase in mRNA and protein expression of SphK1 in mesothelioma cell lines compared to control cell line, and tumor tissues exhibited relatively high levels of SphK1 protein." (PMID 23028939, 2012). "This raises the possibility that there may be two pathways involved in SphK1 dependent mesothelioma cell proliferation." (PMID 23028939, 2012). "Given the positive role of SphK1 in cancer, we hypothesized that high expression of SphK1 may play an important role in the development of mesothelioma." (PMID 23028939, 2012). "To further understand the role of SphK1 in mesothelioma cell proliferation, we next treated the cells with SphK inhibitor and determined the effect on phosphorylation of cyclin dependent kinase 2 (CDK2), which is essential for eukaryotic cell cycle G1/S phase transition." (PMID 23028939, 2012). "Our results thus support the idea that SphK1 signaling in mesothelioma cells may recruit specific HATs." (PMID 23028939, 2012). "In this study, we have demonstrated for the first time, relatively higher protein expression of SphK1, but not SphK2, in mesothelioma cell lines." (PMID 23028939, 2012). "As SphK1 inhibition modulates mesothelioma cell proliferation and histone acetylation, the effect of histone acetyl transferase (HAT) and histone deacetylase (HDAC) inhibition on serum-induced mesothelioma cell proliferation was investigated." (PMID 23028939, 2012). "Our results indicated that SphK1, but not SphK2, regulates mesothelioma cell proliferation through histone acetylation signal transduction." (PMID 23028939, 2012). "In the present study, we demonstrate a definitive role for SphK1, but not SphK2, in supporting the proliferation of mesothelioma cells." (PMID 23028939, 2012). "Using SphK inhibitor and specific siRNA targeting either SphK1 or SphK2, we also unequivocally established that SphK1, but not SphK2, promotes H2691 mesothelioma cell proliferation." (PMID 23028939, 2012). "Down-regulation of SphK1 with specific siRNA for 48 h (>80% loss in specific protein expression, data not shown) attenuated mRNA levels of CBP and p300/CBP-associated factor (PCAF) in mesothelioma cell line H2691, but not the control Met5A cells." (PMID 23028939, 2012). "The mRNA and protein expression profiles of SphK1 and SphK2 were examined in one control (Met5A, non-malignant transformed mesothelioma cells) and three mesothelioma cell lines using real time RT-PCR and immunoblotting with anti-SphK1 and anti-SphK2 polyclonal antibodies." (PMID 23028939, 2012). "Radiation is known to arrest cell proliferation and induce apoptosis in cancer cells; however in a study using malignant mesothelioma cell line exposed to radiation, it was observed that there was no change in p27Kip1 levels thus making SphK1 mediated signaling pathway in mesothelioma cells unique." (PMID 23028939, 2012). "Finally, due to a lack of proper mouse model to investigate mesothelioma, using SphK1 knockout mice, we demonstrated a clear reduction in peritoneal granulamatous tissue as compared to their wild type counterparts when challenged with intra peritoneal injection of multi-walled carbon nanotubes." (PMID 23028939, 2012). "Met5A and mesothelioma cell lines were labeled with [32P]orthophosphate, and cultured in media containing 1% FBS in the presence or absence of exogenous sphingosine, the substrate for SphK1 and SphK2." (PMID 23028939, 2012).
multiple myeloma (4 papers, 2018 to 2024). "Multiple myeloma cells have much higher levels of SphK1, a negative regulator of ceramide accumulation with anti-apoptotic effects." (PMID 38419070, 2024). "Because the amount of SphK1 has been found to be increased in multiple myeloma cell lines and specimens from patients, the combinatorial treatment of 5 μM EGCG and SphK1 inhibitor Safingol was tested." (PMID 30563268, 2018). "Furthermore, through suppression of RTK phosphorylation and activation of death-associated protein kinase 1, the SphK1 inhibitor safingol synergistically sensitized EGCG-induced proapoptotic cell death and tumor suppression in multiple myeloma cells (DAPK1)." (PMID 38419070, 2024). "Additionally, SPHK1 expression was higher in multiple myeloma cell lines U266, ARH-77, RPMI8226, as well as in primary patient cells." (PMID 36361536, 2022). "Similar to SPHK1, SPHK2 was also found to be overexpressed in primary CD1381 multiple myeloma cells, as well as in 7 different myeloma cell lines." (PMID 36361536, 2022).
psoriasis (4 papers, 2019 to 2025). An autoimmune condition characterized by red, well-delineated plaques with silvery scales that are usually on the extensor surfaces and scalp. "To investigate S1P levels in psoriasis, we analyzed the expression of key S1P regulatory genes (SPHK1, SPHK2, and SGPL1) using the psoriasis dataset GSE54456." (PMID 39833165, 2025).
serous ovarian cancer (4 papers, 2016 to 2025). "Progression-free and overall survival were further significantly longer in patients with high-grade serous ovarian cancer and overexpression of SPHK1 (p = 0.002 and p = 0.006, respectively)." (PMID 33660008, 2021). "Univariate Cox-Regression Analysis revealed a highly significant prognostic impact of SPHK1 expression in the subgroup of high-grade serous ovarian carcinoma (HGSOC)." (PMID 33660008, 2021). "Here, we show that SPHK1 is highly expressed in the tumor stroma of high-grade serous ovarian cancer (HGSC), and is required for the differentiation and tumor promoting function of cancer-associated fibroblasts (CAFs)." (PMID 26716409, 2016).
type 2 diabetes (4 papers, 2015 to 2023). "Previous studies have shown that SphK1/S1P plays an important role in regulating stem cell functions and obsesisty and type II diabetes." (PMID 37220155, 2023).
acute leukemia (3 papers, 2011 to 2017). A clonal (malignant) hematopoietic disorder with an acute onset, affecting the bone marrow and the peripheral blood. "SphK1 is overexpressed in various types of cancers including acute leukemia and upregulation of SphK1 has been associated with tumor angiogenesis and resistance to radiation and chemotherapy." (PMID 28555002, 2017). "In myelodysplastic syndromes and acute leukemia, increased gene expression of SphK1 leads to doxorubicin resistance which in reverse can be abrogated by SphK1 siRNA." (PMID 21490804, 2011).
acute pancreatitis (3 papers, 2013 to 2026). An acute inflammatory process that leads to necrosis of the pancreatic parenchyma. "Recently, expression of Sphk-1 and its activity were found to be markedly increased in peripheral immune cells of patients in the early stages of severe acute pancreatitis, indicating that the regulation of the Sphk-1 pathway may represent a novel target in the treatment of this disease." (PMID 23817990, 2013).
cardiac arrest (3 papers, 2017 to 2023). Cessation of breathing and/or cardiac function. "SphK1-knockout mice in a potassium-induced cardiac arrest resuscitation model show reduced S1P levels in tissues and circulation, leading to poor resuscitation and a reduced post-resuscitation survival rate after cardiac arrest." (PMID 36547431, 2022). "A few examples include, mice deficient in SphK1 were rendered lymphopenic by FTY720, endogenous SphK1 demonstrated a protective role in renal ischemia whereas SphK2 had a detrimental role, and in separate studies SphK1−/− mice demonstrated a very poor survival following cardiac arrest." (PMID 28869494, 2017).
cardiac hypertrophy (3 papers, 2017 to 2021). "Our study revealed significant protection against angiotensin II-induced cardiac hypertrophy of Sphk1 knockout mice as compared with wild-type mice." (PMID 33807180, 2021). "Numerous studies have reported that Sphk1/S1P signaling is essential for embryonic cardiac development and promotes pathological cardiac hypertrophy in adulthood." (PMID 33807180, 2021). "Our study also showed for the first time lower cardiac hypertrophy and changes in aortic superoxide anion production following Ang II infusion in Sphk1−/− mice." (PMID 28276483, 2017).
chondrosarcoma (3 papers, 2017 to 2019). A malignant cartilaginous matrix-producing mesenchymal neoplasm arising from the bone and soft tissue. "Additionally, the expressions of SphK1 were negatively correlated with chondrosarcoma progression, indicating that SphK1 may be associated with clinicopathologic stages in chondrosarcoma." (PMID 28672103, 2017). "Surprisingly, our investigations found that treatment of chondrosarcoma cells with S1P and transfecting them with SphK1 cDNA increased PDGF-A expression and induced angiogenesis of endothelial progenitor cells (EPCs)." (PMID 31809267, 2019). "We have previously demonstrated that S1P inhibits the migration of human chondrosarcoma cells and that SphK1 overexpression decreases metastasis to the lungs in a chondrosarcoma xenograft model." (PMID 31809267, 2019). "Meanwhile, the expression levels of SphK1 were negatively correlated with miR‐101 and tumor grades of human chondrosarcoma." (PMID 28672103, 2017). "Our results showed that overexpression of SphK1 significantly suppressed lung metastasis of chondrosarcoma in vivo." (PMID 28672103, 2017). "In this study, we showed that extracellularly applied S1P or overexpressing SphK1 inhibit miR‐101 expression in human chondrosarcoma cells." (PMID 28672103, 2017). "The expression patterns of SphK1 on normal cartilage and chondrosarcoma patients were first assessed." (PMID 28672103, 2017). "Meanwhile, the in vivo study indicated that overexpression of SphK1 decreases chondrosarcoma metastasis to the lungs." (PMID 28672103, 2017). "In summary, higher expressions of SphK1 and TIMP‐3 as well as lower expressions of miR‐101 and MMP‐2 were linked with chondrosarcoma development and metastasis." (PMID 28672103, 2017). "Furthermore, overexpression of SphK1 that generates intracellular S1P suppressed chondrosarcoma metastasis to lungs in vivo." (PMID 28672103, 2017). "Most importantly, SPHK1 overexpression caused a marked reduction in matrix-degrading enzymes and a marked increase in cartilage ECM molecules in miR-103-induced chondrocytes, suggesting miRNA-103 might regulate chondrosarcoma activities by down-regulation of SPHK1, at least, part through SPHK1." (PMID 31652455, 2019). "Indeed, we showed that the Sphk1 decreased in chondrosarcoma tissue, while miR‐101 increased." (PMID 28672103, 2017). "Our results illustrate the clinical significance between SphK1, TIMP‐3, and miR‐101 in human chondrosarcoma patients." (PMID 28672103, 2017). "To confirm the role of S1P in chondrosarcoma cell metastasis in vivo, we took advantage of JJ012 cells that stably express pLenti CMV V5‐Luc (JJ012/Luc) and transfected with SphK1 cDNA." (PMID 28672103, 2017). "Meanwhile, the mRNA expressions of SphK1 and TIMP‐3 of chondrosarcoma tissue sample were lower than those of normal cartilage; however, the miR‐101 expression was opposite." (PMID 28672103, 2017). "The expressions of SphK1 in patients with chondrosarcoma were lower than those in normal individuals." (PMID 28672103, 2017). "Results showed that overexpression of SphK1 inhibited cell migration in human chondrosarcoma cells, while downregulation of SphK1 did not influence the cell migration." (PMID 28672103, 2017). "Moreover, S1P and SphK1 play negative roles on chondrosarcoma metastasis." (PMID 28672103, 2017).
Cirrhosis (3 papers, 2021 to 2025). A chronic disorder of the liver in which liver tissue becomes scarred and is partially replaced by regenerative nodules and fibrotic tissue resulting in loss of liver function. "In a cohort of patients with HCV cirrhosis (n = 216), among which a subset of patients achieved cure (n = 21), high expression of SPHK1 was significantly associated with HCC risk in both cohorts (p < 0.034 for HCV cirrhosis and p < 0.006 for sustained virologic response (SVR), i.e., cure cohorts)." (PMID 33430338, 2021). "Hence, persistent H3K27ac modifications, observed especially in advanced liver disease (F4 fibrosis/cirrhosis), coupled with an elevated SPHK1 expression can be a good HCC predictor in patients reaching SVR." (PMID 35681679, 2022).
clear cell renal cell carcinoma (3 papers, 2019 to 2022). "SPHK1 overexpression contributes to sunitinib resistance in clear cell renal cell carcinoma." (PMID 32630814, 2020).